CD4 (CD4 molecule)
Diseases named in the same sentence as CD4 in open-access papers (continued):
Sharing a sentence is not in itself a finding about the gene and the disease.
tumor (continued). "There were also more CD4+ and CD8+ T cells in the tumor tissues treated with PS/10074-DON than in the other groups." (PMID 36632215, 2023). "The levels of infiltrating CD4 + /CD8 + T cells, Tregs, M1 macrophages, and NK cells in tumor tissues have been shown to be closely related to antitumor immune responses." (PMID 37488178, 2023). "Tregs usually suppress and inactivate effector immune cells including CD4+ T, CD8+ T, and NK cells in the tumor immune microenvironment, facilitating tumor progression." (PMID 37253006, 2023). "Treatment with anti‐PD‐1 induced an increase in the population and activation of CD4+ T and CD8+ T and natural killer (NK) cells in CT26 cancer tissues, an anti‐PD‐1‐responsive tumor." (PMID 37097643, 2023). "In the tumor-draining lymph node, activated APC, e.g., dendritic cells (DCs), present tumor antigens on their major histocompatibility complex (MHC) class I to CD8+ T cells and on MHC class II to CD4+ T cells." (PMID 37511431, 2023). "CD4+ T cells also produce cytokines, such as IFN-γ and TNF-α, which have direct anti-tumor effects and can promote the recruitment and activation of other immune cells." (PMID 37509488, 2023). "CD4+ T cells and CD8+ T cells can hinder tumor growth and metastasis through specific immune responses." (PMID 37170647, 2023). "To test the ability of the DC subsets in relaying CD4+ T-cell help for CD8+ T-cell priming, we established an in vitro tumor antigen-specific CTL priming platform using the primary DC subsets, CD4+- and CD8+ T-cells purified from human blood." (PMID 36639382, 2023). "This combination highlights also the presence of tumor antigen-specific CD8 and CD4 T cells in tumor-infiltrating lymphocytes after the first step of vaccination." (PMID 37516867, 2023). "Some of these immune cells are potentially capable of initiating or exerting anti-tumour activity: these include dendritic cells, CD8+ T cells, Th1 CD4+ T cells, natural killer cells, M1 macrophages and N1 neutrophils." (PMID 36183010, 2023). "CD4+ and CD8+ T cells are essential components of tumor immunity, with CD4+ T cells enhancing immune responses and promoting CD8+ T‐cell activation, while CD8+ T cells directly kill tumor cells." (PMID 37206212, 2023). "We first used the TIMER database to analyse the correlation of VEGFA expression with tumour purity and infiltration of six types of immune cells: CD8+ T cells, CD4+ T cells, B cells, dendritic cells, macrophages and neutrophils." (PMID 36729917, 2023). "In the study cohort, IHC staining revealed that CD3+ T cells, CD4+ T cells, and CD8+ T cells were diffusely distributed in the HCC tumor parenchyma when MPP6 expression was “+”." (PMID 37207207, 2023). "Overall, our in vivo studies depleting CD4+ T cells and employing the CXCR3-blocking Ab highlight infiltration of CXCR3-expressing T cells as a potential mechanism that contributes to tumor regression in the context of this combination therapy." (PMID 36881480, 2023). "The intricate mechanism of VIC-008 involves the activation of CD4+ and CD8+ T-cells and the suppression of Tregs within the tumor microenvironment (TME), contributing to its anti-tumor effects." (PMID 38002286, 2023). "The proportion of T-cells (CD4+, CD8+) in the tumor tissue was found to be highly elevated upon treatment with oxaliplatin or Comp-NPs." (PMID 37660174, 2023). "To do this, we divided primary tumor cells into two subpopulations (primary and pre-nodal) and analyzed the interactions of these two tumor subpopulations with CD8+, CD4+ and T-reg lymphocytes and TAMs." (PMID 36973261, 2023).
tumor (continued). "In a murine tumor model, MIP treatment increases the infiltration and activation of CD4+, CD8+ T cells, NK and NKT cells as well as APCs resulting in secretion of Th1 type pro-inflammatory cytokines in TME." (PMID 37122749, 2023). "Immunostaining of CD8, CD4, and NKp46/NCR1 (used to evaluate natural killer cells) was performed to assess immunity against the tumor." (PMID 36996146, 2023). "Next, we analyzed the exact immune cell infiltration in tumor immune microenvironment and found that MYB expression had a strong correlation with B cell, CD4 T cell, neutrophil and DC in most cancer types." (PMID 36994664, 2023). "Further studies are required to improve our understanding of the regulatory pathway and mechanisms of differentiation of CD4+ TRM cells, particularly in tumor settings." (PMID 37545498, 2023). "C1 displayed an immunosuppressive subtype characterized by high macrophage infiltration, while C2 exhibited higher levels of anti‐tumor TIME components like CD8+ T cells, CD4+ T cells, and B cells." (PMID 37062068, 2023). "By monitoring biomarkers of the immune microenvironment, such as CD4+ and CD8+ T-cell subsets, neutrophil/lymphocyte ratio, cytokines, etc., we can reflect the game status of the immune system and tumor cells." (PMID 37002211, 2023). "To characterize TME features in the two groups along the treatment, we quantified the presence of CD4+ T cells, CD8+ T cells, and CD68+ macrophages in patients’ tumor samples using multiplex IHC." (PMID 37769655, 2023). "The “immune-inflamed” phenotype is characterized by the infiltration of CD4+ and CD8+ T-cells within the tumor, PD-L1 expression in the tumor and high levels of pro-inflammatory cytokines." (PMID 37370830, 2023). "Direct contact between immune cell and tumor organoid led to higher frequency of CD8+ Tem, CD4+ Tcm and Treg cells." (PMID 37470855, 2023). "The proportion of B cells and CD4+ T cells decreased, whereas the proportion of CD8+ T cells increased in Lipo-anti-PD-L1-P4-administrated mice spleens and tumor-infiltrated lymphocytes." (PMID 37492571, 2023). "The knockout also resulted in significant infiltration of CD4+ and CD8+ T lymphocytes in the tumour microenvironment indicating significant immune activation." (PMID 36851335, 2023). "B cells can capture tumor antigens and activate immune cells in the initial stage of the immune response, or participate in tumor killing by secreting antibodies, such as CCL2, CXCR4, CCL5, CXCL5 and CXCL10, which trigger the activation of CD4 and CD8 T cells." (PMID 37254219, 2023). "Overall, the distribution of all subsets of CD4+ and CD8+ T cells shows that the majority of cells are found in the tumor stroma." (PMID 37648263, 2023). "Overall, these data suggest that although HNSCC-56 can present E6 epitopes to CD8+ T cells, E6-specific CD4+ TILs are unable to directly recognize and lyse MHC-II+ autologous tumor cells." (PMID 36512410, 2023). "We evaluated tumor portion (nuclear grade, necrosis, BAP-1, MSLN) and TME portion (CD4, CD8, CD20, CD68, elastic fibers collagen type I and type V fibers) by quantitative digital analyses." (PMID 37901248, 2023). "Motivated by their findings, we simultaneously investigated the spatial heterogeneity in the TME cellular composition of CD14+ cells, CD19+ B cells, CD4+ and CD8+ T cells, and CK+ tumor cells, and their collective impact on the overall survival." (PMID 37756338, 2023). "The addition of CD4+ T cells, especially Th1 cells, can prevent the exhaustion of CD8+ T cells and increase the infiltration of CD8 + T cells, thus leading to effective tumor killing and removal." (PMID 37649123, 2023). "We first evaluated the levels of CD3+, CD4+, and CD8+ TILs in a subset of UPS (n = 50) and DDLPS (n = 32) patients for which there was sufficient tissue to generate tumour microarrays." (PMID 37386008, 2023).
tumor (continued). "Flow cytometry showed a considerable antitumor response after KN046 therapy, with the percentages of CD4+ T cells (12.21% vs. 9.05%) and CD8+ T cells (9.01% vs. 7.40%) in the tumor increasing after treatment with [131I]-KN046 versus KN046 alone." (PMID 36242616, 2023). "Quantitative analyses showed a significant increase in CD4+ (P = 0.00085) and in CD8+ (P = 0.0034) TILs in most analysed paired tumours after CAN-3110 treatment." (PMID 37853118, 2023). "Studies on neoepitope responses have suggested in mouse models the requirement for both CD4- and CD8-mediated responses that act in cooperation to provide tumour therapy." (PMID 38567060, 2023). "Correspondingly, AP203 significantly increased tumor infiltrating CD8 + T cells, while decreased CD4 + T cells, as well as Treg cells (P < 0.05), resulting in a dose-dependent increase in the CD8 + /CD4 + ratio." (PMID 37226226, 2023). "Specifically, we observed more CD4+ and CD8+ T cells, including increased numbers of activated central memory (CD44+CD62L+) and naive (CD44− CD62L+) T cells, after tumour cell engraftment at ZT9." (PMID 36470303, 2023). "The immune score indicated that the percentage abundance of tumor-infiltrating immune cells (endothelial cell, B cell, Macrophage, NK cell, and T cell CD8+) was significantly decreased in cluster 1, but T cell CD4+ were significantly opposite." (PMID 37945610, 2023). "The WT1 Trio vaccine, which includes a helper peptide (WT1-332), was administered in combination in order to activate WT1-specific CD4+ T helper lymphocytes and enhance WT1-specific anti-tumor cellular immune responses." (PMID 36672344, 2023). "Tumor-specific CD4+ T cells can be generated by using MHC-I molecular restrictive TCR, which enhances the tumor-killing ability of specific CD8+ T cells." (PMID 37649123, 2023). "The inhibition of the STING pathway in TAMs upregulated the tumour‐infiltrating CD8+ T cells and CD8+/CD4+ ratio of tumours in vivo." (PMID 37608500, 2023). "We found that several tumor infiltrating immune cells (Act_B cells, Imm_B cells, macrophage cells, Th1 cells, Tfh cells, CD8 + cells, pDC cells, CD4 + cells and Th17 cells) were correlated with the expression of CYFIP2 in cancers using TISIDB." (PMID 37735711, 2023). "In several reports, it was shown that tumor EVs and GBM-EVs had positive effect on proliferation of purified CD4+ T cells." (PMID 36960410, 2023). "We also analyzed the expression of CD4, CD8, Foxp3+, NKp46, TRAIL, PD-1, VEGF, and TGFβ2 to gain additional insights into the tumor immune microenvironment at both the two weeks after treatment initiation timepoint and the EOS timepoint, respectively." (PMID 37446056, 2023). "CD4+ Th1 cells, CD8+ T cells, NK cells, IFN-γ, M1 macrophages uninterruptedly function to be anti- tumor, while regulatory T cells (Treg), M2 macrophages, Th17 cells, overexpression of TGF- β, and IL- 10 facilitates immune evasion of the tumor cells." (PMID 38090593, 2023). "Second, the high frequency spleen CD4 and CD8 T-cells were often identical to the peritoneal T-cells which have previously been shown to be anti-tumor memory T-cells." (PMID 37033929, 2023). "In 2021, the C + I vaccine was proven to stimulate cytotoxic anti-tumor CD8 T cell effector and memory responses, induce cancer-specific humoral immune responses, reduce immunosuppressive CD4 T regulatory cells, and prevent tumor formation in 75% of PDAC mice." (PMID 37755647, 2023). "LncSNHGs can promote apoptosis and suppress the function of tumor-killer cells such as CD4+ T lymphocytes, CD8+ T lymphocytes, and NK cells in tumor immunity." (PMID 37006268, 2023). "Regulatory T (Treg) cells, a subset of CD4+ T cells characterized by the expression of the transcription factor FOXP3, exert a potent inhibitory effect on tumor immunity." (PMID 38169949, 2023).
tumor (continued). "Treatment with the SMOi vismodegib (22 patients) or sonidegib (one patient) for four weeks led to changes in the TME, characterized by increased levels of MHC-I expression in cancer cells and increased infiltration of CD4+ and CD8+ cells in the tumor." (PMID 36674836, 2023). "This resulted in significant infiltration of CD4+ and CD8+ T cells at the tumor site and a low number of CD4+CD25+Foxp3+ regulatory T cells." (PMID 37376125, 2023). "In this network meta-analysis, the clinical effective rate, KPS score, T cell subsets (CD3+, CD4+, CD4+/CD8+), serum tumor markers (CA125, HE4), and adverse reactions were all shown to be 5 interesting outcomes." (PMID 37832073, 2023). "Meanwhile, CD8+ T cells, CD4+ T cells, CD4+FoxP3+ Tregs, CD4+FoxP3− Teffs, and CD68+ TAMs were analyzed in the total, tumor, and stroma area, respectively." (PMID 37674198, 2023). "Immune microenvironment plays an essential role in tumor occurrence and progression, with particularly important players are infiltrating immune cells including CD8+ and CD4+ T cells, macrophages, neutrophils, and dendritic cells." (PMID 36520032, 2023). "At present, it is unclear how these data relate with the expansion of CD4+ T-cells observed in many different models of NASH and how CD4+ T-cells depletion can favour tumour growth." (PMID 36691794, 2023). "CD39 is also a marker of tumor-specific/reactive CD4 + and CD8 + effector T-cells in the tumor microenvironment." (PMID 38057799, 2023). "High immune infiltration means more tumor infiltrating immune cells, so we stained CD3, CD4, CD8, CD20, CD68 to measure the immune infiltration status." (PMID 37593098, 2023). "It is possible that the skewing of these innate immune cells helps to influence or promote the generation of the CD4+ and CD8+ T cell anti-tumor effector cells." (PMID 36875137, 2023). "Profilin, an immunodominant protein in STAg, can greatly promote the infiltration of CD4+ and CD8+ T cells into the TME after intraperitoneal injection into tumor-bearing mice." (PMID 38274735, 2023). "Three subjects had preinfusion and postinfusion tumor tissue analyzed for markers of immune activation (CD3, CD4, CD8), regulatory T cell function (Foxp3) and tumor cell proliferation (Ki67, pS6)." (PMID 37377890, 2023). "Increased CD4+ and CD8+ TCM were detected both in the Treg depletion group and control group after the tumor challenge." (PMID 37407600, 2023). "Here, differences in the function and spatial organization between tumor-infiltrating CD4+PD1+ T cells, Tregs, and malignant CD4+ T cells were correlated with the treatment response of CTCL patients." (PMID 37190290, 2023). "A reduction of the CD4/CD8 ratio was observed within TIL populations, with a fall from 2.7 within blood to 1.1 within the tumor." (PMID 36689623, 2023). "In the tumor microenvironment for immune-cold tumors like GBM, CD8+ T cells often enter an inactivated state and instead CD4+ T cell tumor infiltration is observed." (PMID 36915911, 2023). "Next, we used the TIMER database to analyze the correlation between the expression of S100A10 and tumor purity and the infiltration of CD8 + T cells, CD4 + T cells, B cells, dendritic cells, macrophages and neutrophils." (PMID 37420211, 2023). "Another IDO1 inhibitor increased IDO1 activity in tumor cells leading to increased KYN products, which suppress CD4+ Th1 cells, Th17 cells, CTLs, and NK cells, all of which are overexpressed in malignant tissue." (PMID 37795038, 2023). "Apart from NK cells, which are the dominant mediators in hybrid resistance against parental tumors in the initial phase of tumor implantation, CD4 T cells and CD8 T cells can also recognize tumor-specific antigens in the subsequent stages of tumor progression." (PMID 37033927, 2023). "CD4+ and CD8+ T cells were sorted and used as effector cells in a tumor-killing assay to examine their independent cytotoxicity." (PMID 36915911, 2023).
tumor (continued). "Results indicated a significant increase in PD-1+CD4+ and PD-1+CD8+ T cell proportions within the tumour one day after SBRT completion, but a significant decrease in PD-1+CD8+ T cells seven days post-radiotherapy." (PMID 37600799, 2023). "Flow cytometry showed that the CD4 T cells expressed ICOS+T-bet+ and granzyme B, which are indicative of an anti-tumor phenotype." (PMID 37834397, 2023). "ICOS is expressed on a subset of CD4+ T cells, CD8+ cytotoxic T cells, and most regulatory T (Treg) cells in tumor-infiltrating lymphocytes (TIL), across several indications." (PMID 37593752, 2023). "Here, we further showed that anti-PD-L1 therapy inhibited tumor growth in a CD8+ T cell dependent manner, and CD4+ T cells often exerted opposite effects." (PMID 36969495, 2023). "MDSCs stimulate the production of Treg cells and increase the release of Immunosuppressive cytokines, such as interleukin-10 (IL-10), which specifically suppresses the activities of CD4 + and CD8 + T cells and promotes tumor growth." (PMID 37904131, 2023). "Together, CD4+ T cells and IFN-activated mononuclear phagocytes initiate an indirect inflammatory tumour cell death process that acts from the ‘outside-in’ and can be abrogated by neutralizing IFNγ." (PMID 37316667, 2023). "Similar trends can be seen in BC metastasis, where the microenvironment plays a crucial role in the spread of the tumor, and many immune cells promote immunosuppression and tumor progression, including M2 macrophages, neutrophils, CD8+, CD4+, and Tregs." (PMID 37445860, 2023). "Gene-based delivery of IL-15/IL-15Rα to tumor cells, shows expansion of NK cells, activation of NK cells, CD4+ and CD8+ T cells, and killing of tumor spheroids." (PMID 37923822, 2023). "For further spatial analysis, we quantified the number of CD4+ and CD8+ T cells within the distance gradients of S100A5+CK19+ tumor cells (0‐25 μm, 25–50 μm, 50–100 μm, and 100–150 μm)." (PMID 37414584, 2023). "Transgenic mice lacking LEC-specific MHC-II expression displayed attenuated heterotopic tumor growth, accompanied by elevated numbers of tumor-specific CD8+ and effector CD4+ T cells, as well as reduced numbers of T regulatory CD4+ cells in the TME." (PMID 37744339, 2023). "Whereas the ‘tumor killing’ role mainly corresponds to cytotoxic CD8+ TILs, CD4+ cells contribute to their priming and proliferation." (PMID 37190214, 2023). "Despite without statistical significance, both stromal and intratumoural CD4+ T cells, CD8+ T cells and CD20+ B cells showed a downward trend in infiltration with tumour progression, implying impaired anti‐tumour immune responses." (PMID 37491740, 2023). "Serum CCL5 levels in BCa patients correlated with lymph node metastasis and analysis of Tregs, which promote tumor metastasis, showed CCR5+/CD4+ and Treg/CCR5+ cell ratios were significantly increased in the lymph nodes of the breast cancer metastasis group." (PMID 37759462, 2023). "We demonstrated here that human CD4 CTLs can mediate spontaneous and potent CD8 T-cell-independent tumor control, resulting in protective memory responses in a preclinical tumor model." (PMID 37185301, 2023). "A single dose of tumor vaccine targeting resistant tumors by dual T and NK cells was able to increase CD8+ and CD4+ T cell frequencies by 17.9 and 29.3 fold, and NK cell counts by about 40 fold, respectively, compared to the control in murine models." (PMID 37638022, 2023). "HPV-specific immune mechanisms are involved in tumor clearance; the in vivo antigen-specific antitumor response to HPV+ is mediated by CD4+ and CD8+ T lymphocytes." (PMID 37232820, 2023). "We found that tumor CD4+ T cells and the nearest distance of CD4+PD-1− and CD8+PD-1− to tumor cells at baseline predicted poor survival in ESCC patients." (PMID 37275884, 2023).